SAT2 (spermidine/spermine N1-acetyltransferase family member 2)
Description:
Catalyzes the N-acetylation of the amino acid thialysine (S- (2-aminoethyl)-L-cysteine), a L-lysine analog with the 4-methylene group substituted with a sulfur. May also catalyze acetylation of polyamines, such as norspermidine, spermidine or spermine. However, ability to acetylate polyamines is weak, suggesting that it does not act as a diamine acetyltransferase in vivo.
Synonyms: SSAT-2; SSAT2
Tractability: Small molecule: a structure with a bound ligand is known; it has a high-quality binding pocket. PROTAC: ubiquitination databases record sites on it; its protein half-life has been measured.
Target class: Enzyme; Transferase
Gene: Protein-coding gene on chromosome 17 (7,626,234 to 7,627,876, reverse strand). Ensembl gene ENSG00000141504.
Subcellular location: Cytoplasm
Gene Ontology:
Molecular function: diamine N-acetyltransferase activity; identical protein binding; N-acetyltransferase activity; protein binding; acyltransferase activity, transferring groups other than amino-acyl groups
Biological process: nor-spermidine metabolic process; polyamine biosynthetic process; polyamine metabolic process
Cellular component: extracellular exosome; cytoplasm
Genetic constraint (gnomAD): Loss-of-function variants: 19 observed, 25.98 expected, observed/expected ratio (o/e) 0.73, 90% interval 0.51 to 1.07. The upper end of that interval is the gene's LOEUF score, 1.07, which puts it in group 4 of 6, group 1 being the genes least tolerant of losing a copy. Missense variants: 190 observed, 220.7 expected, observed/expected ratio (o/e) 0.86, 90% interval 0.76 to 0.97. Synonymous variants: 77 observed, 82.78 expected, observed/expected ratio (o/e) 0.93, 90% interval 0.77 to 1.12.
Homologues: Orthologues: chimpanzee SAT2 (99% identical), pig SAT2 (85% identical), guinea pig SAT2 (82% identical), rat Sat2 (81% identical), mouse Sat2 (80% identical), macaque SAT2 (75% identical), Drosophila melanogaster CG4210 (37% identical), Caenorhabditis elegans D2023.4 (34% identical). Paralogues in human: SAT1 (45% identical), SATL1 (41% identical).
Diseases named in the same sentence as SAT2 in open-access papers:
SAT2 is named in the same sentence as 26 diseases in open-access papers, as found by Europe PMC text mining. Sharing a sentence is not in itself a finding about the gene and the disease. The quoted sentences say what the papers report.
Anxiety (1 paper, 2025). Intense feelings of nervousness, tension, or panic often arise in response to interpersonal stresses. "For instance, the path coefficients from PET1 to SAT2 (− 0.31) and PET2 to SAT3 (− 0.39) underscore the efficacy of exercise in diminishing anxiety levels, aligning with Chinese cross-sectional studies that link physical activity with lower social anxiety in adolescents." (PMID 40045423, 2025).
COVID-19 (1 paper, 2021). A disease caused by infection with severe acute respiratory syndrome coronavirus 2. "The CD16+ monocytes in the mild COVID-19 group expressed higher levels of glycolysis-related genes (PGAM1 and GAPDH), a fatty acid-related gene (HACD4), and an arginine and proline metabolism-related gene (SAT2), as well as lower levels of a cysteine and methionine metabolism-related gene (AHCYL1)." (PMID 33936072, 2021).
diabetes (1 paper, 2017). "On the other hand, the α-cell specific Siglec-3 showed a substantial increase in diabetes upon normalization against cyclophilin (PPIA), glucagon or SAT2 (induced to 5.15-, 4.29-, 5.52-fold, respectively in individuals with T2D, vs. non-diabetic controls)." (PMID 28378743, 2017).
foot and mouth disease (1 paper, 2023). A viral infectious disease that results in infection in cattle and swine, has material basis in foot-and-mouth disease virus, which is transmitted by contaminated fomites, or transmitted by ingestion of food contaminated with infected meat or animal products. "In this study, Foot-and-Mouth Disease (FMD) Southern African territory 2 (SAT2) specific primers and TaqMan probe were designed towards rapid SAT2 detection and serotyping." (PMID 37941022, 2023).
leukemia (1 paper, 2024). A malignant (clonal) hematologic disorder, involving hematopoietic stem cells and characterized by the presence of primitive or atypical myeloid or lymphoid cells in the bone marrow and the blood.
Obesity (1 paper, 2010). Accumulation of substantial excess body fat. "In summary, this is the first report of an association between global DNA methylation assessed by ALU/SAT2 methylation and prevalence of CVD, in addition to its risk factors, including male gender and obesity in a population-based Singapore Chinese cohort, a relatively lean population." (PMID 20300621, 2010).
pancreatic cancer (1 paper, 2025). "To further investigate this hypothesis, we next explored the relation of SAT2 expression to immune cell infiltration within pancreatic cancer." (PMID 41150820, 2025).
pemphigus (1 paper, 2025). Pemphigus is a group of rare autoimmune diseases that cause blistering of the skin and mucous membranes (mouth, nose, throat, eyes, and genitals).This conditioncan occur at any age, but often strikes people in middle or older age. "Collectively, these findings indicate that ACSL4, SAT2, and XBP1 exhibit consistent and significant diagnostic value, supporting their candidacy as promising diagnostic biomarkers for pemphigus." (PMID 40612574, 2025). "We also developed a nomogram model integrating the expression scores of ACSL4, SAT2, and XBP1 to predict pemphigus risk, which showed good calibration and significant clinical utility." (PMID 40612574, 2025). "To enhance clinical decision-making, we developed a nomogram model that integrates the expression scores of ACSL4, SAT2, and XBP1 for predicting the risk of pemphigus." (PMID 40612574, 2025). "Differential expression analysis was conducted to investigate the expression patterns of the five genes (XBP1, FBXO45, SAT2, AIFM1, and ACSL4) and eight other DEGs associated with ferroptosis (G3BP1, WBP11, TET2, IRF8, FASN, GDPD5, H1-4, and HUWE1) in both the pemphigus and control groups." (PMID 40612574, 2025). "Results revealed that SAT2 and XBP1 were up-regulated in the pemphigus group compared to the control group, whereas ACSL4 expression was reduced in the pemphigus group." (PMID 40612574, 2025). "The results showed that SAT2 (p = 0.0079) and XBP1 (p = 0.0004) had significantly higher expression levels in the pemphigus group compared to the control group." (PMID 40612574, 2025).
pyrexia (1 paper, 2022). "The SAT2 NI group showed a quicker response time to initial elevation (1 dpi) compared to 1.3 and 1.4 days for SAT1 and 3 NI, respectively (p = 0.01) All animals from SAT1 and one animal from SAT3 NI groups, showed a short second peak of pyrexia at 8 dpi that lasted less than one day." (PMID 35927724, 2022).
renal carcinoma (1 paper, 2025). A carcinoma arising from the epithelium of the renal parenchyma or the renal pelvis. "For instance, in renal cancer, SAT2 has been shown to enhance cisplatin sensitivity under hypoxia by degrading HIF-1α, suggesting a conserved tumor-suppressive mechanism that warrants further cross-cancer comparisons." (PMID 41150820, 2025).
viral infections (1 paper, 2022). "Diagnostic specificity of SAT1, SAT3 and SAT2 topotype VII rRT-PCR assays was revealed to be 100% when evaluated against 18 negative clinical samples and two mock viral infections." (PMID 36204292, 2022).
infection (12 papers, 2013 to 2025). The state of being infected such as from the introduction of a foreign agent such as serum, vaccine, antigenic substance or organism. "As such, these results may be true positive for SAT2 potentially due to a mixed infection or cross-contamination during sample collection." (PMID 36204292, 2022). "The BHK-21-adapted SAT1 and SAT2 viruses were investigated to determine if sulphated compounds could reduce infection of the SAT viruses that attained the ability to infect CHO-K1 cells." (PMID 32991636, 2020). "The duration of detectable genome in serum was similar irrespective to the route of infection and was found to be longer for the SAT1 group (6.5 days) compared to the SAT2 (4.5 days) and SAT3 (2.5 days) in the in-contact groups (p = 0.021)." (PMID 35927724, 2022). "The plaque morphology of SAT2/SAU/6/00 on BHK-21 cells was medium-sized opaque plaques, whereas SAUBHK58 produced large, clear plaques and complete CPE at 24 hours post-infection (hpi)." (PMID 32991636, 2020). "The inoculum contained equal titres of SAT1, SAT2, and SAT3 virus, but only SAT1 was found in infected buffaloes one year after infection." (PMID 31905219, 2020). "To quantify the force of infection, we fit the entire dataset for SAT1 and type O to reverse catalytic models and data for SAT2, SAT3, and A to catalytic models, all of which quantified the time-variation in the force of infection using a b-spline." (PMID 26327324, 2015). "In CHO-K1 (wild-type, glycosaminoglycan or GAG positive) cells, only the SAT2 vaccine strain, ZIM/7/83 and its derivative, vSAT2, were able to propagate, yielding small plaques (<2 mm) 48 h post-infection (p.i.)." (PMID 23717387, 2013). "This suggests that a single R substitution at VP1 112 is tolerated in the SAT2 capsid, but it is insufficient by itself to allow the use of non-integrin receptors to initiate infection." (PMID 40266141, 2025). "Interestingly, at 48 hpi, the non-recombinant parental lines (SP Strain 35 and 38) produced higher yields of SAT1 compared to O, A and SAT2 FMDV, a phenomenon that was also observed following their infection with cell culture-adapted virus." (PMID 35337028, 2022). "Although infection with low-passage SAT1 and SAT2 viruses was predominantly HSPG-independent, several cell culture-adapted strains, each with increased clusters of positively charged residues at the 5-fold axis, attached to cells through an HSPG-dependent mechanism." (PMID 32991636, 2020). "Contrary to the ability of type O1 viruses to utilize αVβ1 and αVβ6 with a high efficiency, the αVβ1 integrins were not able to mediate infection of any of the SAT2 viruses under the experimental conditions." (PMID 23717387, 2013). "Similarly, incubation with anti-SAT2 antiserum blocked subsequent infection with FMDV-SAT2, but not FMDV-SAT1." (PMID 35746633, 2022). "SAT2, DOCK11 and MMP14 were found in both infection and clearance states of Mtb but were not present in control cells." (PMID 34141493, 2021). "Dairy goats immunized with each inactivated chimeric viral antigen, including Om-SAT2-SAU, were not used for challenge tests because of inapparent infection." (PMID 28566375, 2017). "Of note, the infection of non-recombinant suspension cells with cell culture-adapted O FMDV produced lower virus yields compared to infection with cell culture-adapted A, SAT1 or SAT2." (PMID 35337028, 2022). "Analysis of the samples in which FMDV-SAT1 and FMDV-SAT2 were grown in separate cultures and then combined showed that incubation with anti-SAT1 antiserum almost completely blocked the detection of the SAT1 genome in the subsequent round of infection but did not prevent the detection of SAT2." (PMID 35746633, 2022).
cancer (5 papers, 2013 to 2025). A tumor composed of atypical neoplastic, often pleomorphic cells that invade other tissues. "SAT1 and SAT2 regulate polyamine metabolism, a process which has long been implicated in cancer." (PMID 38049632, 2023). "Based on data obtained from the TCGA and GTEx databases, we conducted a comparative analysis of SAT2 gene expression levels in various human cancers and normal tissues." (PMID 41150820, 2025). "Utilizing the Cox regression, the SAT2 level was significantly correlated with OS in six specific cancer types: BLCA, KIRP, LGG, PAAD, UVM and UCEC." (PMID 41150820, 2025). "According to the results obtained from the western blot analysis, it was observed that the cancer cells exhibited lower levels of SAT2 protein compared to the normal cells in five different pancreatic cell types." (PMID 41150820, 2025). "The expression of SAT2 within the PC tissue exhibited a significant decrease in comparison with a non-carcinoma sample." (PMID 41150820, 2025). "SAT2 is the target of DNA methyltransferase 1 (DNMT1) and an epigenetic modifier, whose methylation status may serve as a marker for cancer prognosis." (PMID 23423481, 2013).
tumor (3 papers, 2022 to 2025). "Our study identifies SAT2 as a potential tumor suppressor in PC, with its under-expression associated with larger tumor sizes, poorer prognoses, and altered immune dynamics." (PMID 41150820, 2025). "In summary, SAT2 emerges as a multifaceted regulator in PC, suppressing tumor progression via PI3K/Akt-MAPK inhibition and fostering a less immunosuppressive TIME." (PMID 41150820, 2025). "To investigate the role of SAT2 in PC progression, we conducted a xenograft tumor experiment in nude mice, followed by histopathological analyses including HE staining, TUNEL, and IHC assays on the excised tumor tissues." (PMID 41150820, 2025). "Functionally, our in vitro and in vivo experiments demonstrate that SAT2 overexpression inhibits PC cell proliferation, migration, and invasion while suppressing xenograft tumor growth and promoting apoptosis." (PMID 41150820, 2025). "An in vivo xenograft tumor model was employed for investigating how SAT2 expression affected the PC cell-derived tumor growth." (PMID 41150820, 2025). "The underexpression of SAT2 has been reported in colon cancer, raising the possibility of its tumor-suppressive role." (PMID 41150820, 2025). "The in vivo experimental results suggested the role of SAT2 overexpression in inhibiting xenograft tumor growth." (PMID 41150820, 2025). "In contrast to the Lv-NC group, the Lv-SAT2 group demonstrated an increased number of tumor cells with nuclear condensation, characterized by vacuolation or fragmentation." (PMID 41150820, 2025). "Among all genes connected with CD63, SAT2 is the one with the most significantly differential correlations in tumor and normal tissues." (PMID 36542714, 2022). "Given their pivotal roles in tumor progression and immune regulation, these findings suggest that SAT2 may influence the tumor microenvironment by modulating immune cell function." (PMID 41150820, 2025). "Given its strong correlations with key immune components, SAT2 may have an important effect on shaping the tumor immune microenvironment, and the feasibility of using SAT2 as a therapeutic target should be further investigated." (PMID 41150820, 2025). "SAT2 overexpression significantly suppressed tumor growth in nude mice." (PMID 41150820, 2025). "This suggests that SAT2 may be preferentially expressed in immunosuppressive tumor environments." (PMID 41150820, 2025). "In addition, SAT2 expression showed a close relation to both tumor growth (T stage) and prognosis." (PMID 41150820, 2025). "Spermidine/spermine N1-Acetyltransferase 2 (SAT2), belonging to the spermidine/spermine N1-Acetyltransferase family, has been increasingly recognized for its potential effects on tumor occurrence and development." (PMID 41150820, 2025). "Our findings also highlight SAT2’s impact on the tumor immune microenvironment (TIME), where low SAT2 expression correlates with increased M0 macrophages and decreased anti-tumor cells such as CD8+ T cells and plasma cells." (PMID 41150820, 2025).
adenocarcinoma (1 paper, 2023). A common cancer characterized by the presence of malignant glandular cells. "However, interestingly, expression of SAT1 as well as SAT2 has been linked to improved outcomes in several adenocarcinomas." (PMID 38049632, 2023).
SAT2 also shares sentences with these, for which no sentence is quoted: biliary atresia (1 paper); breast carcinoma (1); co-infection (1); endometriosis (1); hypertrophic cardiomyopathy (1); influenza (1); kidney damage (1); osteosarcoma (1); ovarian carcinoma (1); renal cell carcinoma (1); Stroke (1).